SHH (sonic hedgehog signaling molecule)
Diseases named in the same sentence as SHH in open-access papers (continued):
Sharing a sentence is not in itself a finding about the gene and the disease.
breast tumours (5 papers, 2009 to 2022). "Subsequently we compared GLI1 expression data to previous data on the expression of SHH in the same collective of breast tumours." (PMID 19706168, 2009). "Interestingly the results from our statistical analyses showed a significant association between GLI1 overexpression and the presence of Hh member SHH in human breast tumours." (PMID 19706168, 2009). "This prompted us to check whether any other critical modulators of the pathways related to CSC were altered by the combination treatment and found that the expression of SHH, which is up‐regulated in human breast tumours, is down‐regulated by the combination treatment." (PMID 32720467, 2020). "Significant over expression of SHH (R.E = 4.4 ± 3.32), DHH (R.E = 4.7 ± 3.46), PTCH1 (R.E = 3.4 ± 3.08) and GLI1 (R.E = 3.8 ± 2.49) were detected in the breast tumour biopsies as compared with controls." (PMID 29329585, 2018).
cholangiocarcinoma (5 papers, 2009 to 2021). A carcinoma that arises from the intrahepatic biliary tree (intrahepatic cholangiocarcinoma) or from the junction, or adjacent to the junction, of the right and left hepatic ducts (hilar cholangiocarcinoma). "The non-canonical SHH signaling pathway contributes to the progression of cholangiocarcinoma." (PMID 31979397, 2020).
depression (5 papers, 2020 to 2024). "Recent studies highlight the roles of WNT and SHH signaling in depression and depression-like behaviors, possibly via BDNF-mediated processes." (PMID 37035502, 2023). "In contrast to PTCH +/− mice, SMO-deficient mice, in which SHH signaling is suppressed, exhibit increased anxiety/depression-like behaviors without affecting spatial and fear-related learning ability." (PMID 39290714, 2024). "Abnormal signaling pathways of SHH lead to many neurological diseases, including depression." (PMID 36647544, 2023). "The relationship between the SHH signaling pathway and depression and anxiety has not been established, but SHH may regulate hippocampal neurogenesis in adults." (PMID 39065743, 2024).
Down syndrome (5 papers, 2015 to 2023). "Its dysfunction can cause a number of human developmental defects, such as cerebellar hypoplasia resulting from reduced response of granule cell precursors (GCPs) to the mitogenic effects of SHH, associated with Down syndrome (DS)." (PMID 25540129, 2015). "This overlap in clinical features prompted the hypothesis that some Down syndrome-associated phenotypes result from aberrant SHH signaling and/or ciliogenesis." (PMID 36995257, 2023). "Therapeutic interventions targeting trisomic activators of SHH could worsen SHH-associated phenotypes in people with Down syndrome." (PMID 36995257, 2023). "Trisomic cells derived from individuals with Down syndrome possess deficits in SHH signaling, suggesting that overexpression of human chromosome 21 genes may contribute to SHH-associated phenotypes by disrupting normal SHH signaling during development." (PMID 36995257, 2023). "Our data provide novel insights into the complex genetic architecture of aberrant SHH signaling in Down syndrome." (PMID 36995257, 2023). "In particular, a reduced mitogenic response of cerebellar granule cell precursors to SHH signaling in a mouse model for Down syndrome (DS), Ts65Dn, is substantially responsible for reduced cerebellar size." (PMID 25540129, 2015). "Identification of the genes that modulate SHH signaling may suggest new therapeutic avenues for ameliorating Down syndrome phenotypes." (PMID 36995257, 2023). "Here, we integrate data about cerebellar phenotypes collected in mouse models of Down syndrome, Mendelian disorders, a series of in vitro cDNA screens and RNA sequencing (RNA-seq) analyses to show that the overexpression of multiple human chromosome 21 genes can modulate SHH signaling." (PMID 36995257, 2023).
ependymoma (5 papers, 2017 to 2025). A WHO grade II, slow growing tumor of children and young adults, usually located intraventricularly. "SHH signaling might also have a role in mediating the tumorigenicity of ependymomas due to the upregulation of GLI1-2 and the overexpression of the insulin-like growth factor-2 (IGF-2) ligand, one of the targets of SHH." (PMID 36358663, 2022).
esophageal cancer (5 papers, 2013 to 2020). A primary or metastatic malignant neoplasm involving the esophagus. "As far as we know, the activation of SHH signaling affects all aspects of tumorigenesis, development, and metastasis of esophageal cancers." (PMID 32030915, 2020). "In esophageal cancer, the SHH signaling pathway was extensively activated in xenografts and residual tumors after chemoradiotherapy and blocking SHH signaling enhanced radiation cytotoxicity." (PMID 23762282, 2013). "In recent years, the role of SHH signaling in esophageal cancer has gained extensive attention." (PMID 32030915, 2020). "Recent studies revealed that the activation of SHH signaling not only contributes to the progression of ESCC, but influences the therapeutic outcomes and prognosis of patients with esophageal cancer." (PMID 32030915, 2020). "Similarly, the SHH transcript is localized to tumor tissue whereas GLI1 and PTCH1 are detected in both the tumor and the stroma, proving the hypothesis that SHH and its target genes function in a paracrine manner to regulate the development of subsets of esophageal cancers." (PMID 30423843, 2018).
esophageal squamous cell carcinoma (5 papers, 2011 to 2025). Esophageal squamous cell carcinoma (ESCC) is a type of esophageal carcinoma (EC) that can affect any part of the esophagus, but is usually located in the upper or middle third. "As such, CAF-derived sEVs, which contained highly expressed Sonic Hedgehog (SHH), prominently improve the growth and migration of tumor cells via the Hedgehog signaling pathway in esophageal squamous cell carcinoma (ESCC)." (PMID 39684264, 2024). "For example, CAF-derived exosomal sonic hedgehog (SHH) promotes the growth and progression of esophageal squamous cell carcinoma (ESCC) by binding to the Patched protein to activate the SHH signaling pathway." (PMID 35058933, 2021). "For example, Sonic Hedgehog (SHH) in CAF-derived EVs can promote the proliferation and migration of esophageal squamous cell carcinoma (ESCC)through Hedgehog signaling." (PMID 39935427, 2025). "The overexpression of ATAD2 induces the production of the HH pathway proteins (SHH, SMO, GLI, and PTCH1) in Rb and esophageal squamous cell carcinoma cells (ESCC), which in turn promotes invasion, migration, and proliferation." (PMID 41154392, 2025).
hypospadias (5 papers, 2016 to 2022). Hypospadias is the displacement of the urethral meatus on the ventrum of the penis. "We also identified SROs overlapping with the following genes with established associations with hypospadias: RBFOX2, SHH, and WT1." (PMID 35457073, 2022). "Inactivation of the SHH gene during sexual differentiation can lead to feminization of the genital urinary tracts, such as reduced anogenital distance and hypospadias in males." (PMID 28973975, 2017). "Furthermore, the SHH gene deletion effect is represented by hypospadias, as a consequence of SHH role in genital ectoderm differentiation during urethra genesis." (PMID 31347270, 2019).
myeloma (5 papers, 2012 to 2025). "MM cell lines activate the SHh/Gli1 axis through autocrine SHh, promoting the expression of SHH and Gli1, thereby enhancing proliferation and protecting myeloma cells from spontaneous and stress-induced apoptosis." (PMID 40799240, 2025). "The results showed that the expression levels of PTCH1, GLI2, Hes1, and SHH in RPMI 8226/R were greatly increased compared with the multiple myeloma drug-sensitive cell line RPMI 8226/S, while the expression level of GLI1 was notably decreased." (PMID 35813864, 2022). "In this study, the expression changes of PTCH1, GLI1, GLI2, Hes1, and SHH in the multiple myeloma drug-resistant cell line RPMI 8226/R were first detected." (PMID 35813864, 2022). "Myeloma cells have been reported as the main source of the Hedgehog signaling ligand, sonic hedgehog (SHH), in the BM18." (PMID 33993198, 2021). "Given the evidences on the key role of canonical SHH signaling in modulating the fate of MSCs and differentiation, we established an in vitro coculture system using human MSCs and multiple myeloma cells." (PMID 32019102, 2020). "These evidences support the hypothesis that myeloma cell lines reduce the SHH signaling pathway on MSCs, thus, inhibiting osteoblastogenic differentiation." (PMID 32019102, 2020). "Thus, we hypothesized that MM-MΦ BMI1 upregulation was modulated by Hedgehog signaling via SHH secretion by myeloma cells." (PMID 33993198, 2021). "Our data suggest that the axis between myeloma cell lines (i.e., H929 and OPM2) and MSCs leads to a suppression of the SHH signaling pathway in MSCs, thus, probably reducing the endogenous potential to compensate for osteolytic complications of MM." (PMID 32019102, 2020).
oral squamous cell carcinoma (5 papers, 2016 to 2024). "However, the role of SHH in bone destruction associated with oral squamous cell carcinomas is still unclear." (PMID 27007126, 2016). "In the present study, we analyzed the effect of SHH expression on advanced oral squamous cell carcinomas and how hedgehog signaling was involved in osteoclastic bone resorption associated with tumor invasion." (PMID 27007126, 2016). "In oral squamous cell carcinoma, SHH and GLI1 are both found in the stromal compartment and could be the source of the ligand for both paracrine and autocrine activation in the tumor cells." (PMID 38731849, 2024). "However, the role of SHH in the tumor microenvironment (TME) of oral squamous cell carcinoma (OSCC) is still unclear." (PMID 31744214, 2019). "In conclusion, our results showed that SHH and its signaling molecules were frequently expressed in the tumor bone microenvironment in mandible resected specimens of oral squamous cell carcinoma, and SHH stimulated the differentiation and activation of osteoclasts directly." (PMID 27007126, 2016).
osteosarcoma (5 papers, 2006 to 2023). A usually aggressive malignant bone-forming mesenchymal neoplasm, predominantly affecting adolescents and young adults. "Immunohistochemical staining of Hh ligand using two independent SHH antibodies on 120 human osteosarcoma samples revealed positive staining in 47% of cases and was significantly enriched in high tumor grade and the undifferentiated subtype." (PMID 37845394, 2023). "Using an independent cohort of 40 human osteosarcoma samples, we assessed both SHH expression and primary cilia." (PMID 37845394, 2023). "Variable expression of IHH, DHH and SHH mRNA was detected in all human osteosarcoma cell lines." (PMID 37845394, 2023).
ovarian tumor (5 papers, 2011 to 2021). "Consistent with previous results, GLI1 and GLI3 (HH pathway transcriptional effectors), PTCH1 (HH signaling repressor and target gene), SMO (HH signaling activator), IHH and SHH (HH pathway ligands) were expressed in ovarian tumors, albeit at variable levels." (PMID 26755648, 2016). "In line with the results of the IHC, the protein expression levels of SHH‐F (precursor of the active SHH protein), SHH‐N, and SQSTM1 were dramatically increased in EOC tissues, compared to benign ovarian tumor tissues." (PMID 34076346, 2021). "In addition, we analyzed SHH, SMO, Ptch1, and Gli1 mRNA levels in the 4 individual patient samples we used to generate tumor xenografts for analyzing the effect of Hh pathway inhibition on ovarian tumor growth in vivo." (PMID 22140510, 2011).
pancreatic adenocarcinoma (5 papers, 2010 to 2022). "TAP1 as the downstream target of SHH signaling enhances the drug resistance in pancreatic adenocarcinoma, providing a promising therapeutic approach for the development of more effective targeted therapies in the treatment of PDAC patients." (PMID 36419887, 2022). "Inhibition of SHH signaling could reduce the tumor burden and metastasis in pancreatic adenocarcinomas." (PMID 20230186, 2010). "Initial anti-SHH antibody staining revealed that cSCC tumor cells as well as stromal cells were SHH negative (data not shown) although the malignant epithelium of human pancreatic adenocarcinoma sections showed strong positivity and thus resembles the described SHH expression pattern." (PMID 31867038, 2019).
renal fibrosis (5 papers, 2015 to 2023). A final common manifestation of a wide variety of chronic kidney diseases characterized by glomerulosclerosis and tubulointerstitial fibrosis. "Inhibition of the SHH signal pathway is associated with the inhibition of renal fibrosis." (PMID 35966731, 2022). "The in vivo study aimed to investigate the pathological changes of renal fibrosis, and the effects of rhein on the expression of SHH, Gli1, and Snail proteins were analyzed." (PMID 35966731, 2022). "Taken together, these results demonstrated that rhein suppresses SHH-Gli1-Snail signal pathway activation, with potential implications for the treatment of renal fibrosis." (PMID 35966731, 2022). "Rhein was found to inhibit the SHH-Gli1-Snail signal pathway, which alleviated renal fibrosis in rhein-treated UUO rats." (PMID 35966731, 2022). "During renal development and, as was shown recently, during renal fibrosis, SHH signalling acts in a paracrine fashion." (PMID 28973549, 2017). "Consequently, inhibition of myofibroblast activation and SHH signal pathway may be an effective strategy to prevent renal fibrosis." (PMID 35966731, 2022).
retinoblastoma (5 papers, 2018 to 2025). A malignant tumor that originates in the nuclear layer of the retina. "Besides, miR-361-3p, which is also lowly expressed in retinoblastoma, has been shown to exert a tumor suppressive effect by targeting SHH signaling." (PMID 36590309, 2022). "Also, SHH and WNT pathways were significantly enriched in IO-MEPLs compared to retinoblastomas with increased expression levels of CTNNB1 and SMO." (PMID 34785636, 2021).
rhabdomyosarcoma (5 papers, 2011 to 2022). A rare aggressive malignant mesenchymal neoplasm arising from skeletal muscle. "Comparative expression analysis confirmed specific HHIP-AS1 overexpression in SHH-driven entities including ATRT, cutaneous BCC and rhabdomyosarcoma compared to normal and cancerous control tissues." (PMID 35831316, 2022). "We could verify these phenotypic changes after transient HHIP-AS1 knockdown in additional SHH-driven cell models, namely CHLA-04 (ATRT), RH30 (rhabdomyosarcoma), NSC and UI226 (BCC)." (PMID 35831316, 2022).
Stroke (5 papers, 2017 to 2024). Sudden impairment of blood flow to a part of the brain due to occlusion or rupture of an artery to the brain. "Complete restoration of tube formation in tPA−/−MBECs was observed when both exogenous SHH and tPA were added, demonstrating the role of SHH-induced in vitro cerebral angiogenesis during the brain repair after stroke." (PMID 33494284, 2021). "Following post-stroke, immediate treatment with SHH pathway agonists significantly increased the expression of vasculogenesis-related factors including VEGF, FGF and ANG, together with SHH signaling proteins PTCH1, GLI 1, GLI 2 and SMO." (PMID 30301174, 2018). "This suggests that there may be potential crosstalk between the ferroptosis signaling pathway and the SHH signaling pathway in stroke." (PMID 37351420, 2023). "In cardiovascular patients, endogenous SHH signaling pathway is impaired to varying degrees depending on the severity of the disease such as AMI, stroke and PAD due to the mitigated angiogenic potential of EPCs." (PMID 30301174, 2018).
acute myeloid leukemia (4 papers, 2020 to 2024). Acute myeloid leukemia (AML) is a group of neoplasms arising from precursor cells committed to the myeloid cell-line differentiation. "For refractory acute myeloid leukemia (AML), agents that promote β- catenin degradation; for basal cell carcinoma, hedgehog inhibitors; and for SHH-subtype medulloblastoma and newly diagnosed AML, SMO inhibitors have been tried." (PMID 32580319, 2020). "However, studies with MSCs derived from the bone marrow of patients with acute myeloid leukemia described a decrease in SHh protein expression promoted by 7-KC without changes in Smo expression." (PMID 39518932, 2024).
adenoma (4 papers, 2015 to 2024). A neoplasm arising from the epithelium. "Chung and colleagues found increased adenoma-to-carcinoma conversion with SHH transgene-induced injury, while Dauch and colleagues found that CCl4 could overcome NRas-induced p19Arf tumor suppressor activity, to increase tumor burden." (PMID 39254423, 2024). "Since hormone producing cells of the adenohypophysis as well as ACTH-, GH- and PRL-immunopositive adenomas express SHH and its target GLI1, we furthermore propose that excess HH signaling is involved in the development/maintenance of hormone-producing pituitary adenomas." (PMID 27109116, 2016). "Finally, USP8 has been shown to increase Sonic Hedgehog (SHH) signaling by promoting SMO activity, even if the possible implications of this alteration have not been studied in USP8-mutated corticotrope adenoma cells to date." (PMID 35743266, 2022).
asthma (4 papers, 2019 to 2025). "Kif3a is not only a susceptibility gene locus associated with asthma but also an important kinesin required for ciliogenesis that is known to transduce key extracellular signals, including the sonic hedgehog (SHH) pathway." (PMID 39949885, 2025). "It has also been shown that sonic hedgehog (SHH), an important ligand for PTCH1, is upregulated in the airway epithelium of patients with asthma and is suggested to be involved in airway remodeling." (PMID 36230980, 2022). "Treatment of purified eosinophils from HDM-exposed mice in culture with SHH induces IL4 expression, which illustrates a novel crosstalk mechanism between hedgehog signaling and asthma." (PMID 36230980, 2022). "In another study, SHH protein in the BAL fluid was up-regulated in children with asthma compared to age-matched non-asthmatic subjects, and mice challenged with ovalbumin were also shown to have elevated Shh gene and protein expression in the lungs compared to control mice." (PMID 36230980, 2022). "Collectively, our primary cell data showed an upregulation of SHH, SMO, GLI2 and PTCH1 gene expression with epithelial differentiation independent of a diagnosis of asthma." (PMID 36230980, 2022).
atypical teratoid rhabdoid tumor (4 papers, 2019 to 2025). Atypical teratoid rhabdoid tumor (ATRT) is a highly malignant central nervous system (CNS) rhabdoid tumor (RT) found almost exclusively in children. "The atypical rhabdoid teratoid tumours (AT/RT) were further subclassified into three subtypes: SHH (3, 50%), MYC (2, 33.3%) and TYR (1, 16.7%)." (PMID 41033792, 2025). "Atypical teratoid rhabdoid tumor (ATRT) models represented both Sonic hedgehog (SHH; n = 3) and MYC (n = 3) subgroups, with two models unclassified." (PMID 31693904, 2019). "Atypical teratoid rhabdoid tumors (ATRT) are divided into MYC, TYR and SHH subgroups, suggesting diverse lineages of origin." (PMID 37863903, 2023).
Bardet-Biedl syndrome (4 papers, 2020 to 2023). A ciliopathy with multisystem involvement. "Mutations in SDCCAG8, encoding the sonic hedgehog (SHH) signaling and ciliogenesis regulator, SDCCAG8, cause Bardet-Biedl Syndrome 16 (BBS16)." (PMID 37872160, 2023). "In addition, disruption of SHH signaling has been implicated in neural crest migration defects, which in turn lead to craniofacial abnormalities and HSCR in Bardet-Biedl syndrome." (PMID 36470861, 2022).